KIF5B (kinesin family member 5B)
Diseases named in the same sentence as KIF5B in open-access papers (continued):
Sharing a sentence is not in itself a finding about the gene and the disease.
tumor (35 papers, 2012 to 2026). "siRNA silencing of the anterograde kinesin KIF5B (also known as UKHC) or atypical mitochondria-associated Rho GTPase Miro 1 (left) suppressed the increased tumour cell invasion induced by loss of SNPH." (PMID 27991488, 2016). "The transplantation of the K15:R12 variant of KIF5B-RET fusion gene–transformed cells into nude mice resulted in the development of the tumor in vivo, indicating the fusion gene’s oncogenic potential." (PMID 26268359, 2015). "Consistent with in vitro observations, we also confirmed that the enforced expression of KIF5B-RET caused a significant increase in A549 xenograft tumor weight in nude mice compared with control (KIF5B-RET group vs control group: 0.53 ± 0.2 g vs 0.22 ± 0.15 g, ***P < 0.001)." (PMID 25047660, 2014). "Using these pipelines, we were able to efficiently develop a neoantigen-based vaccine against LUAD tumor cells expressing the KIF5B-RET fusion gene." (PMID 41246330, 2025). "Overall, these results show a strong correlation between low protein expression of either KLC1 or KIF5B and poorer survival outcomes in specific EC tumor classes." (PMID 38388710, 2024). "In a Ba/F3 KIF5B–RET allograft tumor model, 50 mg per kg BID vepafestinib was as efficacious as 30 mg per kg selpercatinib and 60 mg per kg pralsetinib in reducing tumor burden." (PMID 37743366, 2023). "Though with the coexistence of LCNEC and SCC, the tumor is basically adenocarcinoma with KIF5B/RET fusion." (PMID 37653509, 2023). "We used this pipeline to identify KIF5B and SFRP2 as very promising early protein biomarkers secreted by tumor remodulation events associated with cancer cells interacting with naïve stromal cells." (PMID 36002889, 2022). "As for the KPC GEMM mice at different ages, the tumor and stroma were strongly positive for expression of Kif5b at 25 days, 3 months, and 7 months." (PMID 36002889, 2022). "Consistently, tumor tissues from pralsetinib-treated mice had high levels of phosphorylated KIF5B-RET(L730I) and KIF5B-RET(L730V), and active ERK1/2 as in vehicle-treated mice." (PMID 34099825, 2021). "The ORR was 0% for patients with tumor harboring KIF5B as fusion partner with RET, compared to 67% with non-KIF5B partners." (PMID 33671873, 2021). "In contrast, tumor tissues from selpercatinib-treated mice had greatly reduced levels of these activated kinases, indicating that KIF5B-RET(L730I) and KIF5B-RET(L730V) kinases were inhibited by selpercatinib, but not by pralsetinib, in the xenograft tumors." (PMID 34099825, 2021). "Other RET inhibitors, sorafenib and sunitinib demonstrated anti-tumor effects on KIF5B-RET transformed cells." (PMID 29262623, 2017). "In two others, material from the primary tumor showed another two mutations (KRAS p.G12 V mutation and KIF5B-Ret translocation)." (PMID 28693444, 2017). "We evaluated the RET protein expression induced by KIF5B-RET fusion by immunohistochemical analysis of paraffin-embedded tumor tissues with a RET C-peptide monoclonal antibody." (PMID 26268359, 2015). "Total RNA was extracted from the fresh frozen tumor tissues, in which the presence of KIF5B-RET fusion gene was confirmed by both RT-PCR and FISH analysis." (PMID 26268359, 2015). "Imunohistochemical analysis performed on the paraffin sections of the positive tumor tissue revealed moderate, cytoplasmic, non membranal, KIF5B-RET expression in tumor cells." (PMID 25047660, 2014). "RRBP1, a receptor for KIF5B, is involved in vesicle transport or mRNA localization of ER origin and its role of combining ribosomes with kinesins suggests its potential involvement in tumor transport or tumor cell invasion processes." (PMID 41200062, 2026). "The KIF5B [Exon 1-15] | RET [Exon 12- 19] fusion was selected from a patient-derived xenograft (PDX) model based on its established role as an actionable cancer driver in an independent tumor with the same junction." (PMID 41246330, 2025).
tumor (continued). "Therefore, KIF5B-RET-positive tumor cell lines need to be established from clinical specimens to obtain more clinically relevant findings." (PMID 29088743, 2017). "This pathway is centred on molecules that promote (Miro1/2, KIF5B) or suppress (SNPH) the trafficking of mitochondria to the cortical cytoskeleton of tumour cells, a process that provides a concentrated, ‘spatiotemporal' energy source to fuel membrane dynamics and cell movements." (PMID 27991488, 2016). "The expression of the KIF5B-RET fusion gene was analyzed in 154 archival tumor tissues." (PMID 26268359, 2015). "We subsequently measured the protein expression of KIF5B-RET in the positive tumor tissue." (PMID 25047660, 2014). "KIF5B, a member of the Kinesin-1 family, has been extensively investigated and found to play crucial roles in diverse biological processes, including myogenesis, nuclear transport, kidney development, chondrocyte differentiation, viral replication, and tumor progression." (PMID 39507532, 2024). "Tumor invasion assay, another characteristic contributing to cancer invasion and metastasis, was conducted in A549 cell line to assess invasiveness, and indicated that KIF5B-RET fusion gene could also promote invasion of A549 cells with KV2 or KV4." (PMID 27494860, 2016). "This fusion, involving the KIF5B and ALK genes, creates an oncogenic kinase that activates downstream pathways, such as STAT3, promoting tumor growth, migration, and invasion." (PMID 39810398, 2025). "Selpercatinib has been shown to inhibit KIF5B-RET 60 to 1300 times more than MKIs in engineered cells, and significant tumor regression has been seen in RET fusion-positive tumor mouse models." (PMID 37603207, 2023). "APS03118 demonstrated marked anti-tumor efficacy in vivo in RET-driven cell-derived (Ba/F3 KIF5B-RET, V804M, TT (C634W)) and patient-derived (KIF5B-RET, CCDC6-RET, CCDC6-RET V804M) xenograft tumor models at 10 mg/kg (TGI 87–108%)." (PMID 38201460, 2023). "Since KIF5B and SFRP2 had consistent staining in benign and tumor tissue as well as in metastases, they can be considered strong markers and incredibly valuable diagnostically." (PMID 36002889, 2022). "Overexpression of miR-1278 led to tumor growth arrest in vitro and in vivo as well as sensitization to oxaliplatin by increasing DNA damage and apoptosis by binding with the 3′UTR of KIF5B, a member of the kinesin family in CRC." (PMID 33791222, 2021). "Based on the data from the TCGA COAD program, we found that KIF5B and CYP24A1 were significantly overexpressed in tumor samples compared to normal tissues." (PMID 33791222, 2021). "In our study, the average frequency of the RET break-apart probes 23.9 % (range, 14.8–37.8) and KIF5B-RET fusion 44.4 % (range, 22.2-72.4)in 9 tumor tissues." (PMID 26268359, 2015). "Additionally, KIF5B-ALK fusion promotes the transition from the G1 to the S phase by activating cyclin-related proteins, such as cyclin D1, further facilitating tumor progression." (PMID 40852483, 2025). "To assess the affinity of the junction neopeptides formed by the KIF5B-RET fusion gene expressed and presented by the tumor, we employed two sequence-based in-silico HLA affinity prediction pipelines and a pipeline to examine Class I HLA affinity from a structural standpoint." (PMID 41246330, 2025). "Here, we demonstrate that mice lacking Kif5b (the heavy chain of kinesin-1) in their DCs exhibit a major impairment in cross-presentation and thus a poor in vivo anti-tumour response." (PMID 32286311, 2020). "Unfortunately, native tumor cell lines with KIF5B-RET are not available or reported to our best knowledge." (PMID 29088743, 2017). "Here, we screened for known KIF5B-RET fusions in Chinese NSCLC patients using real-time polymerase chain reaction (RT-PCR) and corroborated the oncogenic activity of this fusion kinase by colony formation and tumor formation assays." (PMID 25047660, 2014).
tumor (continued). "IMT is the tumor that most frequently overexpresses ALK protein, however, in addition to no expression of skeletal muscle markers Myo-D1, Myogenin and Myogenin, genetically, IMT usually shows ALK re-arrangement with many other molecular partners including TPM3, KIF5B, CARS, and THBS1." (PMID 36998041, 2023). "Treatment of Ba/F3 KIF5B–RETWT allograft tumors with vepafestinib (12.5, 25, 50 mg per kg BID) resulted in dose-dependent inhibition of tumor growth without any body weight changes." (PMID 37743366, 2023). "A KIF5B-RET and EML4-ALK fusion were readily detected in the positive control patient-derived xenograft and cell line, but no fusions were detected in 5 of 5 tumor samples." (PMID 39052387, 2024). "Notably, two samples that were equivocal or negative by FISH (13% and 18% of rearranged tumor nuclei) were found to be positive by NGS, with KIF5B as the fusion partner, pointing toward the importance of checking both borderline positive and borderline negative samples." (PMID 39507413, 2024). "In conclusion, we used a murine conditional knockout model (lacking Kif5b in all hematopoietic lineages) to demonstrate that kinesin-1 regulates Ag cross-presentation in the cDC1 and cDC2 subsets and thus is essential for an effective CD8+ T-cell-mediated anti-tumour response." (PMID 32286311, 2020).
cancer (31 papers, 2009 to 2026). A tumor composed of atypical neoplastic, often pleomorphic cells that invade other tissues. "The ability of these neopeptides to bind to a broader range of HLA alleles will increase the applicability of this vaccine to cancer patients expressing the KIF5B-RET fusion." (PMID 41246330, 2025). "The data presented here suggest that KIF5B is implicated in several pathwaysinvolving lysosomes and that its highly expressed in all cancer cell lines tested,as compared to other N-Kinesins including KIF5A/KIF5C (Kinesin 1 family), KIF3A(Kinesin 2 family) and KIF1A (Kinesin 3 family)." (PMID 19242560, 2009). "This study aimed to use peptides to prime the immune system to recognize and respond to MHC Class 1 presented neoantigenic peptide sequences from the KIF5B-RET fusion protein expressed in LUAD cancer patients." (PMID 41246330, 2025). "Kinesin family member 5B (KIF5B), for instance, has been connected to lysosome transport in autophagy, and its depletion led to perinuclear accumulation of autophagosomes in cancer cells." (PMID 40395516, 2024). "Our data demonstrate that KIF5B is highly expressed in cancer cells and plays asignificant role in growth and survival of HeLa cells." (PMID 19242560, 2009). "To elucidate therole of KIF5B in cancer cells we examined its function in various lysosomal pathwaysincluding the lysosomal cell death pathway, the resealing response after plasmamembrane damage (exocytosis) and macroautophagy." (PMID 19242560, 2009). "Our data identify KIF5B as a cancer relevant lysosomal motor protein withadditional functions in autophagosome formation." (PMID 19242560, 2009). "Furthermore, yeast two-hybrid analyses have indicated that the C-terminal region of RRBP1 interacts with the kinesin family member 5B (KIF5B), which has markedly high expression in a variety of cancer cell lines, such as MCF-7, HeLa and U2OS cells." (PMID 41200062, 2026). "We synthesized alkynyl nicotinamide-based RET TKIs and tested their efficacy in cell cultures in inhibiting selpercatinib/pralsetinib-resistant RET solvent-front mutants G810C/R/S found in cancer patients, and in BaF3/KIF5B-RET(G810C) cell-derived subcutaneous and intracranial tumors in vivo." (PMID 40496186, 2025). "As observed earlier with Loxl2, Kif5b staining in cancer cells and immediate stroma showed a strong positivity while in the normal pancreas, the acini were strongly positive but adjacent stroma was weakly positive for Kif5b expression." (PMID 36002889, 2022). "In a large study involving multiple advanced cancers types, using a hybrid-capture targeted 70-gene cfDNA test, KIF5B-RET fusion was dominant in NSCLC, and that non-KIF5B-RET fusion contributed to anti-EGFR resistance, highlighting the importance of knowing the specific gene partner." (PMID 34915883, 2021). "Kinesins such as KIF11, KIF25 and KIF5b are overexpressed in most cancer cells." (PMID 33292489, 2020). "Their findings also suggested that RRBP1 may participate in the accumulation of perinuclear autophagosomes in cancer cells by interacting with the kinesin family member 5B (KIF5B)." (PMID 31285390, 2019). "Additionally, a recent study has shown that expression of the oncogenic fusion between the KIF5B kinesin motor protein and the Ret tyrosine kinase, KIF5B-Ret, promotes many hallmarks of cancer in tracheal epithelial cells." (PMID 29693007, 2018). "RET gene fusions have been reported as driver genes for various types of cancer, including thyroid, lung, intestine, pancreas, and breast, and fusions such as CCDC6-RET, NCOA4-RET, and KIF5B-RET are known to be frequently seen." (PMID 40647546, 2025). "A population-wide examination of TT and LN single cells found that primary cancer overexpresses NOTCH2, NOTCH2NL, KIF5B, and ERBB4 but that metastatic cancer overexpresses CDK12, ERBB2, and CLDN11." (PMID 37322261, 2024).
cancer (continued). "This suggests that KIF5B and SFRP2 have great potential to be early biomarkers that are consistently expressed in both cancer mouse models and clinical samples." (PMID 36002889, 2022). "In addition, we found in this list established cancer genes involved in other types of cancer, such as PDE4DIP, SF3B1, AHNAK, COPB2, CSDE1, KIF5B, NDUFA10, RSRC2." (PMID 31949199, 2020). "Apatinib exerted its anti-cancer effect not only via cytotoxicity, but also via inhibition of migration and invasion by suppressing RET/Src signaling pathway, supporting a potential role for Apatinib in the treatment of KIF5B-RET driven tumors." (PMID 27494860, 2016). "Similarly to the findings in our previous study showing that the depletion of KIF5B is more toxic to HeLa cells than to MCF7 cells, we observed some differences in the sensitivities of the different cancer cell lines to the identified siRNAs." (PMID 23071517, 2012). "However, the relatively unique and less prevalent nature of mutations, such as the oncogenic driver KIF5B-RET fusion, should not deter studies from examining it, but instead, prompt the development of personalized treatments for each cancer type." (PMID 41246330, 2025). "In addition, evidence showed that higher KIF5B and ERBB4 promoted cancer cell proliferation." (PMID 33441952, 2021).
infection (8 papers, 2016 to 2023). The state of being infected such as from the introduction of a foreign agent such as serum, vaccine, antigenic substance or organism. "This hypothesis seems to be unlikely since the CCV was not disrupted when the cells were transfected with the plasmid encoding KIF5B after the formation of the CCV (48h post-infection, unpublished data)." (PMID 30640917, 2019). "Quantification of heavy-chain fluorescence intensity on virions in WR-infected cells demonstrated that IEVs recruited 4.13-fold more KIF5B than IMVs, despite the latter making up the majority of virions assembled during infection." (PMID 36093836, 2023). "The role we identify for Kif5B and the other kinesins found in our screen in early infection seems to be the predominant one in this system." (PMID 29782552, 2018). "Up to ~30 min p.i., Kif5B-mediated transport delays virus redistribution to the nucleus and retards infection." (PMID 29782552, 2018). "Kif5B knockdown did, in fact, reduce Ad5 infectivity, supporting a role for kinesin-1 in aiding the virus in the early stages of infection." (PMID 29782552, 2018). "After ~30 min p.i., Kif5B-dependent assisted diffusion enables more efficient cytoplasmic exploration by the virus and stimulates infection." (PMID 29782552, 2018). "The net inward movement was most prominent from 15–30 min p.i., supporting a normal role for Kif5B in MT plus end-directed Ad5 transport during the early stages of infection." (PMID 29782552, 2018). "During infection, KIF5B mediated anterograde trafficking of viral cores is accompanied by the displacement of Nup358 from the nuclear membrane to the cytoplasm, where it associates with viral cores." (PMID 27327622, 2016). "Western blot analysis of Nup358 and KIF5B showed efficient depletion of each protein at the time of infection." (PMID 27327622, 2016). "Following synchronized infection, we observed that depletion of KIF5B delayed HIV-1 uncoating, as measured by p24 staining of individual GFP-Vpr puncta." (PMID 27327622, 2016). "Collectively, these data demonstrate that HIV-1 induces NUP358 relocalization during infection in a CA and KIF5B dependent manner." (PMID 27327622, 2016). "To investigate the role of Nup358 and KIF5B in HIV-1 uncoating, we looked at the uncoating states of individual virions following a synchronized infection in cells depleted of Nup358, KIF5B or both proteins by siRNA using an in situ uncoating assay." (PMID 27327622, 2016). "Given the defective nuclear entry observed following KIF5B and Nup358 knockdown, we examined the ability of HIV to associate with Nup358 during infection." (PMID 27327622, 2016). "We also monitored the effects of Kif5B RNAi on virus behavior later in infection (30–60 min), when directed movements are still seen, but the distribution of virus in the LMB-treated cells has reached a steady state, with no clear bias in transport toward or away from the cell center." (PMID 29782552, 2018). "In considering the mechanisms by which NUP358 and KIF5B might mediate this effect, two aspects of infection should be considered." (PMID 27327622, 2016). "However, we observed that Nup358 or KIF5B knockdown reduced nuclear import and infection of WT virus, consistent with previous reports." (PMID 27327622, 2016). "Knockdown and overexpression of kinesin-1 heavy chain (Kif5B) suppressed and promoted CSFV proliferation, respectively, at indicated time points post-infection." (PMID 37766277, 2023). "In our study, introducing a 25-amino acid dominant-negative Kif5b fragment in uncoating decreased VSV cellular entry, indicating the potential application of CHC-binding peptide in impeding VSV infection." (PMID 30603101, 2018). "We observe that infection and nuclear import of WT HIV-1 is perturbed by KIF5B knockdown, consistent with recent observations by us and others." (PMID 27327622, 2016).